AGT (angiotensinogen)
Diseases named in the same sentence as AGT in open-access papers (continued):
Sharing a sentence is not in itself a finding about the gene and the disease.
Insulin resistance (224 papers, 2004 to 2025). Increased resistance towards insulin, that is, diminished effectiveness of insulin in reducing blood glucose levels. "The M235T polymorphism of the angiotensinogen gene is related to insulin resistance in PCOS patients, and the genotype of ACE is related to the occurrence and development of PCOS women." (PMID 38195648, 2024). "Insulin resistance and inflamed adipose tissue cause an increase in adipose-derived angiotensinogen and conversion of angiotensin I to angiotensin II." (PMID 32785000, 2020). "A relationship between the AGT gene, AGT levels, and insulin sensitivity in humans has been suggested with an association between AGT M235T polymorphism and increased insulin resistance." (PMID 29484134, 2018). "These hypothesized factors are sympathetic nervous system activation, genetic predisposition, insulin resistance and release of detrimental inflammatory adipocytokines by intra-abdominal adipose tissue as well as release of cortisol and angiotensinogen." (PMID 32822432, 2020). "Polymorphisms of the angiotensinogen gene have been associated with insulin resistance in both sexes, increased risk for central obesity and dyslipidemia in hypertensive women with metabolic syndrome, and with visceral obesity and insulin resistance in obese Japanese women." (PMID 31262355, 2019). "In addition, the higher level of concentrations of adipocytokines are associated with fluctuations in the levels of angiotensinogen, plasminogen activator inhibitor-1, interleukin-6, and resistin, which might progress the onset of insulin resistance and atherosclerotic lesions." (PMID 38536210, 2024). "Adipocyte hypertrophy is associated with reduced secretion of leptin and adiponectin, together with enhanced secretion of insulin resistance inducers, blood coagulation promoters, monocyte chemoattractant proteins, and angiotensinogen." (PMID 37107219, 2023). "It is showed that AGT expression increased in the adipose tissue of obese animal models and adipocyte-specific enhancement of AGT lead to insulin resistance, indicating the special role of adipose tissue RAS in regulation of metabolic homeostasis." (PMID 35802723, 2022). "This fat increment was also related to insulin resistance in obese patients, and its angiotensinogen production during cardiac surgery can induce postoperative insulin resistance." (PMID 35887234, 2022). "For example, overexpression of AGT in adipose tissue increases adiposity and blood pressure and leads to insulin resistance." (PMID 23308073, 2012). "REN, a key enzyme in the renin–angiotensin system (RAS), initiates the conversion of angiotensinogen to angiotensin I. Its elevated activity in T2D contributes to increased oxidative stress and inflammation, exacerbating insulin resistance and beta cell dysfunction." (PMID 39195477, 2024). "Moreover, insulin resistance is associated with the renin-angiotensin system (RAS), in which the initial action of renin cleaves angiotensinogen to angiotensin I (ANG I), then ANG I converts to ANG II by the angiotensin converting enzyme (ACE)." (PMID 36112580, 2022). "In brief, these relationships demonstrated that angiotensinogen and ACE were found in adipocytes in obese humans, thereby raising the possibility that ANG II was produced locally and could exert local effects contributing to insulin resistance." (PMID 29462993, 2018). "Moreover, as one of the pro-inflammatory adipokines, overproduction of angiotensinogen from adipose tissue was found to induce adipose inflammation, glucose intolerance and insulin resistance." (PMID 28529466, 2017). "Furthermore, stress-induced insulin resistance could also contribute to the increase in angiotensinogen." (PMID 25551221, 2014). "However, it is unclear whether targeted inactivation of AGT in adipose tissue would specifically alter fat mass and such studies would convincingly confirm the role of adipose AGT in modulating insulin resistance or fat mass." (PMID 23308073, 2012).
Insulin resistance (continued). "Also, the findings that VAT secretes fewer genes linked to inflammation and insulin resistance, such as Tnf and angiotensinogen, and that SAT does not inflame but instead secretes a significant amount of adiponectin can also be interpreted as supporting the prior assumption." (PMID 41385510, 2025). "Known safety concerns were validated, including elevated non-fasting insulin (insulin resistance), and elevated angiotensinogen (salt retention)." (PMID 27530235, 2016). "However, hepatic AGT knockout attenuated weight gain and improved insulin resistance specifically in female HFpEF mice, with no such benefits observed in males." (PMID 40888605, 2025).
Hyperglycemia (217 papers, 2004 to 2025). An increased concentration of glucose in the blood. "After a series of medical studies on rats and biopsy samples of human kidneys, scientists confirmed the association between hyperglycemia, ROS and angiotensinogen (AGT) gene expression." (PMID 34445675, 2021). "The SGLT2 inhibitor was successful in normalizing the systolic blood pressure of diabetic mice, in addition to the hyperglycemia-induced rise in renal angiotensinogen mRNA and urine 8-isoprostane levels." (PMID 37566054, 2023). "Expression of renal proximal tubular angiotensinogen (AGT) is affected by hyperglycemia, which stimulates AGT expression via enhanced oxidative stress." (PMID 37566054, 2023). "These other components include angiotensinogen at the proximal tubules and renin release by the macula densa, as seen with hyperglycemia-induced mitochondrial succinate production acting on the GPR91 receptor." (PMID 37566054, 2023). "Various research indicates that hyperglycemia enhances the transcription of angiotensinogen and consequently angiotensin II, therefore enhancing the RAAS activity." (PMID 36826542, 2023). "Hyperglycemia also increases angiotensinogen production in glomerular mesangial cells, podocytes, and endothelial cells." (PMID 34289001, 2021). "In in vitro studies of proximal tubular cells, SGLT2 inhibitors suppressed the hyperglycemia-induced production of reactive oxygen species and angiotensinogen." (PMID 31938043, 2020). "The etiology of the intrarenal RAAS characteristic of DM is incompletely understood but has been commonly attributed to the effect of ambient hyperglycemia on angiotensinogen generation." (PMID 23861950, 2013). "Hyperglycaemia directly upregulates intracellular synthesis of angiotensin-II and high glucose stimulates angiotensinogen gene expression and cell hypertrophy." (PMID 22545680, 2012). "Treatment with 2,3,5,4′-tetrahydroxystilbene-2-O-β-d-glucoside could inhibit hyperglycaemia-induced mRNA and protein expression of AGT, renin, ACE, and AT1R in mice with DN induced by streptozotocin." (PMID 36059935, 2022). "Moreover, the presence of hyperglycemia stimulates AGT mRNA expression in the proximal tubule of the kidney, and this increased gene expression is likely mediated by the reactive oxygen species (ROS)." (PMID 36013381, 2022). "Under diabetic conditions, hyperglycemia may increase angiotensinogen generation and Ang II production in the kidney." (PMID 34790127, 2021). "Hyperglycemia also enhances ANG-II production by the stimulation of angiotensinogen and RAAS." (PMID 34884494, 2021). "Literature has shown that hyperglycemia increases transcription of angiotensinogen, ACE and Ang II." (PMID 30170598, 2018). "Thus, evidence suggests that the generation of ROS and AGT is markedly increased once the vicious cycle of hyperglycemia and inflammation increasing ROS, AGT, and angiotensin II (Ang II) to further enhance ROS and AGT is activated in the DN kidney." (PMID 24489716, 2014). "Hyperglycemia significantly upregulated VEGF-A and AGT in both RPE and HREC cells (e.g., VEGF-A in RPE: 2.62-fold, P = 0.001; AGT in RPE: 3.32-fold, P = 0.093), supporting a role for both osmotic and glucose-specific pathways." (PMID 40510890, 2025). "In conclusion, this study demonstrated that hyperglycemia significantly upregulates VEGF-A and AGT expression in both RPE and HREC cells, underscoring a potential role for AGT in the pathophysiology of DR." (PMID 40510890, 2025).
Hyperglycemia (continued). "This study provides valuable insights into the effects of hyperglycemia on VEGF-A and AGT expression in two physiologically relevant retinal cell types and highlights the differential impacts of various insulin analogues." (PMID 40510890, 2025). "Interestingly, C66 administration does not affect angiotensinogen and renin expression, but significantly reduced ACE mRNA levels (P < 0.001), indicating that the reduction in Ang II level by C66 may result from its inhibition of hyperglycaemia-induced ACE overexpression." (PMID 24330074, 2014). "Additionally, IR-induced hyperglycemia upregulates the expression of angiotensinogen, angiotensin-converting enzyme (ACE), and angiotensin II, leading to overactivation of the renin–angiotensin–aldosterone system (RAAS)." (PMID 40964523, 2025). "Changes in angiotensin II, angiotensinogen and noradrenaline in response to hyperglycemia were not significant in either group." (PMID 23861950, 2013). "Regarding AGT among the offspring of GDM mothers, the influence of intrauterine exposure of hyperglycemia was suggested, although genetic factors of T2DM could not be distinguished because of high genetic predisposition to T2DM related to GDM." (PMID 29329330, 2018).
renal fibrosis (217 papers, 2009 to 2026). A final common manifestation of a wide variety of chronic kidney diseases characterized by glomerulosclerosis and tubulointerstitial fibrosis. "A renal fibrosis model was established in mice induced by angiotensinogen II (Ang II) and its sheddase, metalloprotease-17." (PMID 40224489, 2025). "Related to glomerular and renal tubular injury, AGT has the highest correlation with the degree of renal fibrosis in IgAN patients." (PMID 38390575, 2024). "Angiotensinogen murine knockout studies have demonstrated that angiotensin II expression is responsible for at least 50% of renal fibrosis in chronic neonatal UUO." (PMID 28286898, 2018). "Urinary angiotensinogen levels were also evaluated to explore the role of RAS with soluble klotho in renal fibrosis." (PMID 29590173, 2018). "In conjunction with our results, it remains to be determined whether increased AGT secretion via MAP kinases due to reactive oxygen stimulation is involved in renal fibrosis." (PMID 40362266, 2025). "The possible mechanism is that AGT can increase inflammatory factors and reactive oxidation factors via angiotensin II, induce the formation of crescent in renal tissue and aggravate the degree of renal fibrosis." (PMID 38390575, 2024). "Additionally, sKlotho supplementation reduces renal angiotensinogen and angiotensin II levels, followed by the amelioration of renal fibrosis in diabetic and adriamycin nephropathy." (PMID 31275449, 2019). "We also focused on the role of RAS in klotho-renal fibrosis axis, especially intrarenal RAS activity, which was assessed based on urinary angiotensinogen." (PMID 29590173, 2018). "Angiotensin II induces the expression of TGF- β 1 and angiotensinogen genes, and induces the proliferation of renal interstitial fibroblasts through AT1 receptors, which may be involved in the pathogenesis of renal fibrosis." (PMID 35720359, 2022). "Urinary angiotensinogen was also not adequately correlated with the degree of renal fibrosis and other pathological findings in our study, although other studies suggested that urinary angiotensinogen represented a potential marker of deterioration of kidney function." (PMID 29590173, 2018).
myocardial infarction (208 papers, 2008 to 2026). Gross necrosis of the myocardium, as a result of interruption of the blood supply to the area, as in coronary thrombosis. "A genetic polymorphism that increases the level of circulating AGT in the blood is related to a higher risk of myocardial infarction." (PMID 39511582, 2024). "The polymorphism of the angiotensinogen M235T genotype occurs more frequently in patients with acute myocardial infarction than in the healthy control subjects." (PMID 38279313, 2024). "AGT M235T polymorphism plays a vital part in the pathogenesis of many cardiovascular disorders (including myocardial infarction, ischemic heart disease, CAD)." (PMID 36557328, 2022). "The terms “myocardial infarction”, “angiotensinogen”, and “polymorphism” were used to search the China Biological Medicine Database China National Knowledge Infrastructure, Embase, PubMed, and Web of Science." (PMID 34025779, 2021). "The T174M polymorphism in the AGT gene was further identified to associate with the risk of myocardial infarction in a meta-analysis study." (PMID 31142626, 2019). "The presence of the AGT M235 homozygote was associated with a 2-fold increase of myocardial infarction risk." (PMID 25984491, 2014). "Besides, the notion of some of the AGT variants or their interactions with such disease risk traits playing a role in CAD/myocardial infarction (MI) has been refuted by a number of studies in various ethnic groups." (PMID 23497386, 2013). "It has been suggested that the angiotensinogen (AGT) gene rs4762 (p.Thr174Met) polymorphism might be associated with myocardial infarction (MI) risk, but the study results are still debatable." (PMID 34025779, 2021). "Furthermore, according to the approach that investigates negative genes with high positive probability as output by the DNN, the gene AGT is associated with brain diseases and neoplasms; and the gene TNF is associated with myocardial infarction." (PMID 31845988, 2020).
fibrosis (182 papers, 2008 to 2026). the formation of excess fibrous connective tissue in an organ or tissue in a reparative or reactive process. "Therefore, we inferred that C3 AGT + Fibroblasts are more sensitive and active than other fibroblast subpopulations for the progression of cardiomyopathy as well as fibrosis." (PMID 38799173, 2024). "Nevertheless, QFHXD and prednisone decreased ACE, AGT, and AT1R protein expressions (vs fibrosis group, P<0.01)." (PMID 36594067, 2023). "Collectively, these data suggest that cardiac fibrosis and inflammation are not the key contributors to hepatic AGT‐regulated HFpEF in male and female mice." (PMID 40888605, 2025).
diabetic nephropathy (150 papers, 2006 to 2025). "Various gender specific studies showed the significant association of AGT M235T gene polymorphism with diabetic nephropathy in males as compared to females among various populations." (PMID 36557328, 2022). "AGT M235T polymorphism increases the plasma level of AGT which increases the risk for diabetic nephropathy." (PMID 36557328, 2022). "AGT has been linked to an increase in reactive oxygen species in diabetic nephropathy." (PMID 40003909, 2025). "The polymorphism of AGT M235T leads to the replacement of methionine with threonine amino acid (M235T) and a substitution of the T to C base at 702 nucleotides on exon 2 results in the development of diabetic nephropathy." (PMID 36557328, 2022). "However, the mechanism underlying the onset and progression of diabetic nephropathy in relation to the expression and secretion of angiotensinogen (AGT) in the kidneys remains unclear." (PMID 40003909, 2025). "However, the mechanisms underlying the increased AGT expression and secretion observed in patients with diabetic nephropathy remain unclear." (PMID 40362266, 2025). "Additionally, levels of AGT, a biomarker reflecting tubular injury, were significantly elevated, suggesting that C. sinensis infection may increase the risk of diabetic nephropathy." (PMID 39840062, 2024). "In this review, we present an overview of the intrarenal RAS and its role in diabetic nephropathy, as well as reviewing the evidence for the use of urinary AGT as a biomarker of this system in diabetic nephropathy." (PMID 40003909, 2025). "Research has demonstrated that the amount of AGT excreted in urine is useful as an early biomarker of diabetic nephropathy." (PMID 40003909, 2025). "To explore new possibilities for such foods or food components, we examined how AGT is involved in the progression of diabetic nephropathy and how soy isoflavones act to suppress this fluctuation." (PMID 40003909, 2025). "In recent years, it has been shown that TGF-β/Smad2 is downstream of AGT and is involved in fibrosis in diabetic nephropathy." (PMID 40362266, 2025). "We previously investigated the effects of polyphenols, which have high antioxidant properties, on AGT—an early marker of diabetic nephropathy." (PMID 40003909, 2025). "Research has shown that urinary AGT is an early biomarker of diabetic nephropathy, and this has been confirmed by several other studies." (PMID 40362266, 2025). "We reported the importance of urinary angiotensinogen as an early marker for the onset of diabetic nephropathy and showed that it increases more sensitively than urinary albumin." (PMID 40003909, 2025). "We previously reported that angiotensinogen (AGT) expression is elevated in patients with diabetic nephropathy." (PMID 40362266, 2025). "Activation of the intrarenal RAS was also involved in diabetic nephropathy, and urinary AGT was increased in T2D model rat." (PMID 26380312, 2015). "The activated oxidative stress/AGT/RAS axis is important in the pathogenesis of diabetic nephropathy." (PMID 24284398, 2013). "In rodent models, it has been reported that reactive oxygen species (ROS) are important for intrarenal angiotensinogen (AGT) augmentation in the progression of diabetic nephropathy." (PMID 24284398, 2013). "Clearer evidence of AGT expression in human proximal tubules is, therefore, important for understanding the development and progression of diabetic nephropathy." (PMID 24284398, 2013). "Of all the markers tested for association with diabetic kidney disease, ins/del polymorphisms in ACE and Met235Thr SNP in AGT genes are the two most extensively studied." (PMID 16672053, 2006). "The “question” of this study is whether soy isoflavones—a type of polyphenol—are involved in the mechanism of the progression of diabetic nephropathy through the expression and increased secretion of AGT as an early marker of diabetic nephropathy." (PMID 40003909, 2025).